BRCA1 (BRCA1 DNA repair associated)
Diseases named in the same sentence as BRCA1 in open-access papers (continued):
Sharing a sentence is not in itself a finding about the gene and the disease.
tumor (continued). "Moreover, we applied Monocle to reconstruct the transformation trajectories from normal mammary cells to tumor cells in the BRCA1 mutation carrier and found that the levels of replication stress showed an increasing trend during the process of LP transformation into tumor cells." (PMID 41498327, 2026). "Since HRR is vital for maintaining genomic integrity by accurately repairing DNA double-strand breaks, mutations in BRCA1/2 compromise this repair pathway and lead to tissue-specific predisposition for breast and ovarian cancer, highlighting the unique roles of these genes in tumor biology." (PMID 41373752, 2025). "Moreover, the ratio of CD4+ T cells and CD8+ T cells near proliferating tumor cells in BRCA1/2-deficient tumors is positively correlated with patient prognosis, suggesting that the coordination of immune surveillance through the spatial connection of cells improves the prognosis of patients." (PMID 40830526, 2025). "Similarly, BRCA1/2-mutated tumours have also been reported to respond better to platinum therapies." (PMID 40394000, 2025). "However, it is not clear whether this is simply a consequence of the genetic instability associated with the BRCA1 mutation or if it is promoted by factors accelerating tumor formation." (PMID 40136510, 2025). "Through its role as a transcriptional coactivator of RRM2, high expression of BRCA1 may mask its functional defects, leading to inefficient DNA damage repair, thereby promoting genetic mutations and instability in tumor cells and accelerating tumor progression." (PMID 41497799, 2025). "However, emerging evidence suggests that certain genetic profiles, such as BRCA1/2 mutations, high tumor mutational burden (TMB-H), or microsatellite instability-high (MSI-H), may confer increased sensitivity to these therapies." (PMID 39741969, 2024). "Finally, we determined the effect of BRCA1 or BRCA2 loss on in vivo tumor growth." (PMID 39028933, 2024). "However, certain genetic profiles, such as BRCA1/2 mutations, high tumor mutational burden (TMB), or microsatellite instability-high (MSI-H), may enhance sensitivity to these therapies." (PMID 39741969, 2024). "Besides playing its role in protecting tumor cells from chemo‐ and radiotherapy, cPD‐L1 also participates in the process of tumor resistance triggered by Breast Cancer Susceptibility Protein‐1 (BRCA1), which regulates DNA repair through homologous recombination." (PMID 37934012, 2024). "Damage to the double helix could therefore be repaired through HR; however, if the cell (in this case a tumor cell) has a mutation of BRCA1/2 or other genes involved in DNA repair mechanism, the result is the cell cycle arrest, chromosomal instability and cell death." (PMID 38525421, 2024). "Based on the outgoing signal of VEGFA from fibroblasts to TECs and the causal relationship between VEGF and tumor angiogenesis, we investigated the expression levels of diverse genes associated with pro-angiogenic factors and the endothelial index between TECs and NECs in BRCA1 MT TNBC patients." (PMID 38182557, 2024). "However, carriers of BRCA1 mutations may also show functional haploinsufficiency, which increases the risk of overt neoplasia." (PMID 38149669, 2024). "Since the HR status can change over time due to evolutionary tumor and treatment selection and cell lines are exposed to genetic drift, we hypothesized that functional HR status better reflects real-time HR status than BRCA1/2 mutation status." (PMID 38398132, 2024). "Our findings also suggest that targeting this newly discovered fork recovery pathway might represent a promising strategy to selectively kill BRCA1-deficient tumor cells and highlight the possible predictive utility of measuring levels of these fork recovery factors in tumor samples." (PMID 38943334, 2024).
tumor (continued). "Surprisingly, in both the Brca1- and Brca2-deficient tumour models used in this study, the in vivo treatment with anti-PD-L1, whether as a monotherapy or in combination with olaparib, resulted in a systemic increase in nearly all the studied immune cells presenting surface PD-L1." (PMID 38017453, 2023). "BRCA1/2 gene mutation may explain the high proportion of TNBC tumor in young patients." (PMID 36895689, 2023). "Finally, NVB reduces tumor growth in a PDX model with BRCA1 and 53BP1 loss of function." (PMID 37569269, 2023). "Similarly, the 5-year survival rate is shorter for patients with BRCA1-mutated tumours." (PMID 38017453, 2023). "Thus, a tumor was defined as HRD-positive if the HRD score was ≥42 or BRCA1/2 was mutated." (PMID 37258600, 2023). "Furthermore, it has been suggested that HRD and BRCA1/2 alterations could induce tumorigenesis by increasing the number of tumor mutations and, possibly, the number of neoantigens." (PMID 37761329, 2023). "Average percentage concordance for evDNA with the tumor was determined to be 100%, whereas for cfDNA concordance was lower with 88.89%, suggesting that evDNA may have a slight advantage for the detection of BRCA1 variants in patients." (PMID 35205822, 2022). "Therefore, treatment strategies for BRCA1/2 mutation carriers should contain information dissemination and education about the beneficial effects of physical activity before and after tumor occurrence to improve the participants’ attitude towards physical activity." (PMID 35190584, 2022). "A BRCA1 c.5074G > A p.(Asp1692Asn) variant detected in the first female at 42 years, classed as likely pathogenic, was found in ~ 52% of reads in DNA extracted from tumour, ~ 10% of reads in DNA extracted from peripheral blood leukocytes and ~ 10% of reads in DNA extracted from buccal mucosa." (PMID 36068545, 2022). "Furthermore, while mechanistic implications of BRCA1/2 in GC pathogenesis remain obscure, there is evidence that GC may be enriched for mutations in genes associated with HR and confer a tumor mutation signature associated with HR deficiency." (PMID 36497436, 2022). "In the same manner, tumor patients carrying germline BRCA1/2 variants cannot accurately repair DNA damage following the administration of chemotherapy drugs and similar anti-tumor treatments, and as a result, may also have increased risk or elevated severity of adverse reactions." (PMID 35847868, 2022). "Two seminal papers in 2005 established the synthetic lethality between PARP inhibition and BRCA1/2 loss in preclinical models and these data, in conjunction with the proof-of-concept phase I study of olaparib, underpin the therapeutic strategy for PARPi in patients with BRCA1/2 mutant tumours." (PMID 36497408, 2022). "Furthermore, the possible associations with tumor morphology and BRCA1 expression have also been investigated to better define patients that could benefit from combinatorial therapies with PARPs and AKT inhibitors." (PMID 35053468, 2022). "Therefore, tumor cells with defective HR, such as those with a BRCA1/2 mutation, are susceptible to impairment of PARP, facilitating cell death, or can be alternatively repaired by the error-prone NHEJ pathway, resulting in genomic instability before cell death." (PMID 35572596, 2022). "However, insights into human PC tumor biology show that many patients with advanced disease may exhibit molecular changes in pathways unrelated to AR, such as BRCA1 and BRCA2 mutations, genes involved in DNA repair (BRCA1/2)." (PMID 35681707, 2022). "In addition to patients with tumours containing BRCA1 or BRCA2 pathologic variants, there is emerging evidence that patients with tumours harbouring pathologic variants in other HR genes may also benefit from PARPi therapy." (PMID 36011309, 2022).
tumor (continued). "Advanced ovarian cancer patients with BRCA1/2 germline mutation, treated with platinum-based neo adjuvant chemotherapy prior to surgery, may be expected to have less tumor volume at the time of surgical cytoreduction as compared to those patients without a BRCA1/2 germline mutation." (PMID 36363568, 2022). "Third, as acknowledged below in limitations we are unable to determine if the origin of mutations in cfDNA in our study is from tumor or germline and this may also have increased the incidence of BRCA1 alterations as compared to historical tissue somatic testing results." (PMID 36185208, 2022). "Hormone receptor positivity may even indicate a less favorable prognosis for young women, with a higher risk of distant relapses, therefore a tumor model for BRCA1 loss of function together with hormone receptor positivity is relevant for evaluating new treatment strategies." (PMID 36333737, 2022). "In addition, inherited BRCA1 or BRCA2 germline mutations may dramatically increase the risk of secondary tumors in “normal” tissue encompassing the tumor, which is also partly irradiated during radiotherapy." (PMID 35057061, 2022). "Additionally, debate is still ongoing whether the association between tumor size and outcome is as strongly present in BRCA1/2-associated BC." (PMID 35507134, 2022). "Although PARPis can lead to a ‘synthetic lethal’ interaction with HRD, the compensatory effects of other DNA damage repair pathways, BRCA1/2 recovery mutations, high expression of drug resistance pumps, and changes in tumor metabolism may cause acquired PARPi resistance." (PMID 36230574, 2022). "This study suggests that BRCA1/2 variant carriers treated with BCT have survival rates at least comparable to those treated with mastectomy with radiotherapy or mastectomy alone and that BCT could be an option for BRCA1/2 variant carriers when the tumor is clinically appropriate for BCT." (PMID 33890992, 2021). "When BRCA1 is mutated, DNA double strand breaks remain unrepaired by homologous recombination which contributes to genomic instability that may result in transformation of cells and further tumor evolution." (PMID 34611475, 2021). "The aggressive behavior of BRCA1-deficient tumors could be attributed to the random mutations that occur in the genome of these cells due to HR deficiency, which can result in the activation of oncogenes or inactivation of tumor suppressors." (PMID 35008272, 2021). "Several studies have highlighted that BRCA1/2 mutated OC harbor a higher number of tumor specific neo-antigenes and demonstrate increased expression of the immune checkpoint modulators, PD-1 and PD-L1, which indicated that BRCA1/2 mutated OC may be more sensitive to PD-1/PD-L1 inhibitors." (PMID 34966689, 2021). "However, the large size and the lack of mutational hotspots in these genes make traditional Sanger sequencing-based diagnosis, even for the diagnosis of germline BRCA1/2 mutations, laborious and time consuming and, for somatic mutations, unreliable due to tumor heterogeneity." (PMID 34068254, 2021). "Moreover, the close relationship between BRCA1 promoter allele methylation levels and tumor cell content support a view that the hypermethylation is already present in the main clone, as opposed to subclonal, and therefore early in evolution of the tumor." (PMID 32719340, 2020). "In addition, we describe a computational model for the assessment of BRCA1/2-associated genomic DNA methylation patterns in tumor tissues and examine the ability of this classifier to distinguish the patients that may benefit form PARP inhibitor therapy." (PMID 32483276, 2020). "Accumulation of R-loops may also occur by the loss of tumour suppressors such as BRCA1/2." (PMID 32098397, 2020). "Mutations in the BRCA1 gene may result in unregulated cell growth and tumor development." (PMID 32013256, 2020).
tumor (continued). "Therefore, it became important to evaluate whether a tumor-testing-first strategy would be the most cost-effective option, allowing for the simultaneous detection of both germline and somatic BRCA1/BRCA2 variants." (PMID 32850417, 2020). "Furthermore, among the 15 patients with loss-of-function of BRCA1/2 (nine tumors with BRCA1 hypermethylation, five tumors with BRCA1 mutation and one tumor with BRCA2 mutation), SigMA identified ten to be Sig3 positive, again consistent with the reported sensitivity of the SigMA algorithm." (PMID 32193378, 2020). "In addition, an inverse relationship between BRCA1 and TILs was found, hypothesizing that BRCA1-mutated tumors could have more tumor-specific neoantigens and, therefore, increased TILs." (PMID 31540486, 2019). "Besides, women with BRCA1 or BRCA2 mutations presented different tumor and FH profiles." (PMID 31244284, 2019). "Patients harboring pathogenic/likely pathogenic tumor BRCA1/2 mutations may be eligible for PARPi therapy, according to clinical characteristics, and directed to genetic counseling, during which a peripheral blood sample will be tested to evaluate the germline nature of the alteration identified." (PMID 31653094, 2019). "Thus, simultaneous inhibition of RAD52 and PARP1 might result in a robust dual synthetic lethality, effectively eradicating BRCA1/2-deficient tumor cells." (PMID 31615159, 2019). "Importantly, BRCA1/2‐deficient cells with acquired resistance to olaparib or cisplatin show sensitivity to chlorambucil, suggesting its therapeutic potential against this difficult to treat tumour subset." (PMID 31273933, 2019). "In addition, the serum tumor markers combining BRCA1/2 mutation status could also predict metastasis status." (PMID 30972954, 2019). "However, a higher frequency of BRCA1/2 mutations was identified among patients with the tumor BRCA test requested at least 6 months after diagnosis without disease-relapse (34.3%) as compared with patients with the test performed at diagnosis or disease relapse (29.3% and 16.2%, respectively)." (PMID 31653094, 2019). "predicted prognosis accurately in patients from France, Canada, and those with low grade tumours, but less accurate in patients from UK, Ireland, Malaysia, South Korea, Taiwan, those with lympho-vascular invasion, BRCA1-mutation carriers, and those with high grade tumours." (PMID 30871490, 2019). "However, it remains elusive whether estrogen stimulates proliferation of ER-negative BRCA1-deficient tumor cells in vivo through activation of the Akt pathway." (PMID 29996906, 2018). "In the same study the survival of patients with tumours harbouring NER alterations was similar to patients with BRCA1/2-altered tumours suggesting that NER pathway alterations may contribute to EOC platinum sensitivity to a similar extend as that of the effect of BRCA1/2 loss." (PMID 29925418, 2018). "Notably, tumor-associated BRCA1 mutants are defective in suppressing ERα transcriptional activity." (PMID 30558184, 2018). "Besides, by comparing the presentation of dominant parameters among specific mutations subgroups, BRCA1‐mutated tumours were found with higher levels of potent immunotherapy‐responsive signatures, providing a rational for the ICIs treatment for BRCA1‐mutation carriers with HGSOCs." (PMID 29855141, 2018). "Notably, cyclin D1 and PCNA were induced in BRCA1-deficient tumor tissues." (PMID 30652068, 2018). "Interestingly, TNBC is associated with an increased deoxyribonucleic acid (DNA)-repair defect in the tumor cells, which is caused either by germline mutations in genes such as BRCA1/2, PALB2, and others or by a somatic HRD, which can be exploited by systemic therapies." (PMID 30373556, 2018).
tumor (continued). "Therefore, how a patient would response to platinum therapy is dependent not only on the occurrence of mutations that functionally inactivate BRCA1/2 but also to a large degree on other cellular mechanisms such as ion transport pathways that influence the dynamics of the drug within the tumor." (PMID 29459887, 2018). "“BRCAness” is a relatively recent concept in tumor biology that capitalizes on the fact that defects in error-free DNA double-strand break repair by HR repair represent a common outcome of inactivating mutations in a large number of genes in addition to BRCA1 or BRCA215,40." (PMID 29748622, 2018). "BRCA1 expression tended to be lower in older age and in patient with positive family history however, the associations (with basal markers, tumor grade, AR, hormone receptors, bcl2 and Ki67 index) persisted after adjusting for age at diagnosis and family history." (PMID 28863181, 2017). "We hypothesized that the ternary complex may play a role in BRCA1-deficient tumor cell growth." (PMID 29158484, 2017). "The results of subgroup analyses for OS stratified by study quality, tumor stage, study design, sample size, number of research center, duration of follow-up, baseline characteristics adjusted and tumor histology were mostly constant across BRCA1/2, BRCA1 and BRCA2 mutation subtypes." (PMID 27690218, 2017). "However, RxRxH mutation altered the tumour suppressor activity of BRCA1." (PMID 27402801, 2016). "Thus, the specific functions of BRCA1 in the mammary gland and steroid hormone signalling might possibly explain the tissue specificity of tumours arising in BRCA1-mutation carriers." (PMID 27881737, 2016). "Thus, the study of tumor phenotypes associated with BRCA1/2 mutations may be useful to predict the probability to carry a germline mutation." (PMID 27129401, 2016). "This study provides insight into the pattern of CpG methylation across the BRCA1 promoter, and supports previous studies suggesting that tumours with BRCA1 promoter methylation have similar features to those with BRCA1 mutations, and therefore may be suitable for the same targeted therapies." (PMID 27463681, 2016). "The identification of this pathogenic mutation, found only in the tumor sample, confirms the value of testing for tumor BRCA1/2 mutations, and identifies patients with germline and somatic BRCA mutations who may be eligible for treatment with PARP inhibitor drugs such as olaparib." (PMID 27793035, 2016). "In addition, we evaluated whether any clinical or tumor pathologic features predicted for AR+, PD-L1+, or BRCA1-associated TNBC." (PMID 28721372, 2016). "However, tumours in BRCA1 mutation carriers were more likely to present with more advanced stage (42.9 % vs. 23.5 %, P for trend = 0.11) and were more frequently ER− (9.7 % vs. 3.3 %, P = 0.17) and PR− (21.4 % vs. 13.2 %, P = 0.27) than tumours in BRCA2 mutation carriers." (PMID 26857456, 2016). "The BRCA1 protein is involved in many essential cellular processes that include DNA damage signaling and repair, cell-cycle control, protein ubiquitination, cell differentiation, and gene transcription regulation, all of which are associated with its tumor suppressor function." (PMID 27246982, 2016). "Similarly, loss of function due to germline or somatic deletions in tumour suppressor genes may confer drug sensitivity, such as that of high grade serous ovarian cancer with BRCA1 or BRCA2 mutations, to the PARP inhibitor olaparib." (PMID 26569395, 2015). "Of note, a recent study investigating the role of Ezh2 in a Brca1 deficiency-based model of mammary tumorigenesis found that deletion of Ezh2 shortens the latency of tumor formation, further reinforcing the view that the enzyme might inhibit breast tumorigenesis." (PMID 26637281, 2015).